TNF (tumor necrosis factor)
Diseases named in the same sentence as TNF in open-access papers (continued):
Sharing a sentence is not in itself a finding about the gene and the disease.
anxiety disorder (48 papers, 2012 to 2026). A category of psychiatric disorders which are characterized by anxious feelings or fear often accompanied by physical symptoms associated with anxiety. "The pro-inflammatory cytokines involved in CRS, such as IL-6 and TNF-α, have been well implicated in the pathophysiology of mood and anxiety disorders, as inflammation is increasingly recognized as a contributor to psychiatric conditions." (PMID 40094890, 2025). "A similar report has established an increase in TNF-α and IL-1β were associated with mood and anxiety disorders." (PMID 35769902, 2022). "Pro-inflammatory cytokines such as TNF-α, IL-17, and IL-6 have been variably associated with mood and anxiety disorders; however, published data remain inconsistent, with reports of both upregulation and downregulation depending on disease context, population, and methodology." (PMID 41598638, 2026). "Proinflammatory cytokines, including IL-6 and TNF-α, have been implicated in the etiologies of clinical anxiety disorders, which may affect the IGF-1 concentration." (PMID 37151979, 2023). "The presence of increased inflammatory mediators, such as TNF-α, leads to activation of microglia and recruitment of peripheral blood monocyte entry into the brain parenchyma that is associated with pain, depressive and anxiety disorders." (PMID 34512420, 2021). "It was found that the levels of TNF-alpha, interleukins 4 and 10, as well as IgG, were higher in patients with anxiety disorders." (PMID 40289955, 2025). "TNF, a major inflammatory and immune mediator, has been extensively studied for its role in cardiovascular diseases and anxiety disorders." (PMID 39470548, 2024). "Consistent with this analysis, we found elevated levels of IL-1β, TNF-α, IL-6, and IL-4 expression among children with TD, whereas state anxiety among those children correlated positively with IL-17 levels." (PMID 38956051, 2024). "Overall, these findings provide insight into the role of TNF-α in opioid withdrawal and the development of anxiety disorders such as PTSD." (PMID 33580871, 2021). "In another study which included patients with rheumatoid arthritis receiving anti-TNF-α therapy had less frequent prevalence of any mood or anxiety disorders demonstrating a beneficial role of anti-inflammatory therapy in anxiety disorders." (PMID 29181395, 2017). "The aim of this study was to explore potential relationships between sera TNF-α levels and mood and anxiety disorders in SLE patients." (PMID 26732584, 2016). "As for PSAC-induced anxiety, it has been linked with elevated pro-inflammatory markers, such as in a cohort study showing that elevated CRP was observed in male patients with anxiety disorders; another study found increased TNF-α in patients with anxiety disorders." (PMID 39802655, 2025). "Additionally, physical activity reduces systemic inflammation by lowering pro-inflammatory cytokines (IL-6, TNF-α, CRP), which are linked to the onset and progression of anxiety disorders." (PMID 41246056, 2025). "Furthermore, patients with depressive or anxiety disorders exhibited increased levels of cytokines such as interleukin-6 (IL-6) and tumor necrosis factor-α (TNF-α)." (PMID 35705957, 2022). "Cytokines such as tumor necrosis factor α and transforming growth factor β, which are involved in depressive and anxiety disorders, may also initiate the EMT in GBM." (PMID 33113511, 2020). "Reports have shown that cytokines such as interleukin (IL)-6, tumor necrosis factor-alpha (TNF-α), IL-10, and monocyte chemoattractant protein-1/CCL2 might be well associated with depressive, bipolar, or anxiety disorders." (PMID 29740354, 2018). "Therefore, corticosterone is utilized as a marker for assessing stress in studies of humans and animals alike; additionally, elevated levels of pro-inflammatory cytokines such as TNF-α, IL-1β, and IL-6 may serve as biological markers of anxiety disorders." (PMID 33628177, 2020).
anxiety disorder (continued). "In the context of anxiety disorders, the most studied inflammatory markers are CRP, interleukin (IL-6), and tumor necrosis factor-α (TNF-α)." (PMID 35923828, 2022). "The levels of pro-inflammatory cytokines such as tumor necrosis factor (TNF)-α and interferon (IFN)-γ are elevated in serum of patients suffering from anxiety disorder." (PMID 35345530, 2022). "↔ in patients with GAD compared with controls, and ↔ between TNF-α and GAD compared with other anxiety disorders." (PMID 31326932, 2019). "The level of inflammatory biomarkers, tumor necrosis factor (TNF)-α, interleukin (IL)-6 and C-reactive protein (CRP) among people with anxiety disorders have been studied by observing how they interact with neurotransmitter systems, especially serotonin and dopamine, it influences mood and behavior." (PMID 40421256, 2025). "This suggests that CORT, inflammatory factors (IL-6, IL-1β, CD86, TNF-α, TGF-β, IL-10), 5-HT, and GABA may serve as biomarkers for anxiety disorders." (PMID 40078708, 2025). "Another study included 70 patients with generalized anxiety disorder (GAD), and found that GAD patients had significantly elevated serum cytokines, including TNF-α, but serum TNF-α levels were significantly reduced after successful treatment of anxiety disorders." (PMID 39295596, 2024). "Higher levels of pro-inflammatory peripheral cytokines have been identified both in models of anxiety disorders (tumor necrosis factor-α [TNF-α] and interleukin [IL]-1 β, IL-6), as well as mood and anxiety disorders patients (c-reactive protein [CRP], TNF-alpha, IL-1, IL-6,)." (PMID 34680430, 2021). "Sera TNF-α levels are increased in SLE patients with mood and anxiety disorders." (PMID 26732584, 2016). "In summary, sera TNF-α levels are increased in SLE patients with mood and anxiety disorders." (PMID 26732584, 2016). "Recently, a metanalysis on 1077 anxiety disorders patients showed that, excluding patients with a chronic organic illness, moderately higher concentrations of pro-inflammatory markers (again mainly IL1-β, IL6, and TNF-alpha) were present in patients’ blood, compared to healthy controls." (PMID 34680430, 2021). "In individuals with current depressive or anxiety disorders compared to healthy controls, elevated levels were observed in CRP, IL-6, IL-8, IL-18, MCP-1, MIP-1α, MIP-1β, MMP2, and TNF-β, while TNF-α, IL-10, IFN-γ, IL-2, and IL-4 levels either showed no significant elevation or were lower." (PMID 39273641, 2024).
autoimmune hepatitis (48 papers, 2013 to 2026). Hepatitis caused by autoantibodies. "Among these, TNF inhibitors such as infliximab are frequently implicated, with reports highlighting autoimmune hepatitis as a recognized adverse effect." (PMID 39913410, 2025). "There is no data regarding the distribution of genotypes in Caucasian population with NASH, but it was demonstrated that the A allele and AA genotype represent a risk factor for autoimmune liver diseases due to an increased production of TNF-α." (PMID 28852433, 2017). "We showed that shikonin can attenuate autoimmune hepatitis caused by ConA through the inhibition of the release of proinflammatory cytokines, such as IL-1β, TNF-α, and IFN-γ." (PMID 27293314, 2016). "The development of autoimmune hepatitis is closely associated with the release of proinflammatory cytokines, including IL-1β, TNF-α, and IFN-γ." (PMID 27293314, 2016). "Recent research has shown that autoimmune hepatitis was associated with the release of large amounts of inflammatory cytokines, such as TNF-α, IL-6, IL-1β and IFN-γ, leading to apoptosis and necrosis in liver pathology." (PMID 25761053, 2015). "Other studies have shown that TNF-α -308G/A and -238G/A polymorphisms may contribute to increased susceptibility to autoimmune liver diseases (AILD) in Caucasians." (PMID 39958350, 2025). "Another SNP in the TNF gene rs1799724 is associated with CD and autoimmune hepatitis (AIH)." (PMID 32328064, 2020). "Honghua is the primary specific plant component of HHXY, and its main active ingredient, hydroxyl safflor yellow A (HSYA), significantly reduces TNF-α and IL-17 levels in experimental autoimmune hepatitis mouse models, thereby alleviating autoimmune attacks." (PMID 40584613, 2025). "Other research groups have shown similar synergistic effects of IL-17 and TNFα in autoimmune liver disease and on oligodendrocytes." (PMID 36862362, 2023). "For instance, in autoimmune liver diseases, NKT cells release death signals to hepatocytes through FasL pathway, and secrete TNF-α, perforin and granzymes in synchronization, promoting the process of autoimmune liver diseases." (PMID 36389715, 2022). "In the Con A model of autoimmune hepatitis, hepatic macrophages/monocytes are the main TNFα producing cell type, and TNFα released by these cells drives downstream innate and adaptive immune responses within the liver." (PMID 31031775, 2019). "A few arguments link the TNFα signaling pathway to pathogenesis of autoimmune hepatitis, mostly the high levels found in liver and blood of patients compared to controls." (PMID 31616649, 2019). "Limited data on the efficacy of anti-TNF-α in patients with autoimmune hepatitis and primary biliary cholangitis are also available." (PMID 30060508, 2018). "Recently, anecdotal evidences of efficacy of anti-TNF-α agents as rescue therapy in difficult-to-treat autoimmune hepatitis (AIH) and primary biliary cholangitis (PBC) have been reported." (PMID 30060508, 2018). "A study of cytokine levels in children with autoimmune hepatitis discovered a correlation between the levels of TNF-α, IL-6, and IL-8 and disease activity in patients with type 1 AIH." (PMID 28299346, 2017). "Several studies show that the release of inflammatory cytokines is involved in autoimmune hepatitis, including IL-1β, TNF-α, IFN-γ, and IL-6, giving rise to the development of liver injury." (PMID 27293314, 2016). "Pretreatment with resveratrol ameliorated the pathologic effects of ConA-induced autoimmune hepatitis and significantly inhibited IL-2, IL-6, TNF-α, Shh, Gli-1, and Ptc." (PMID 26089871, 2015). "IL-2, IL-6, TNF-α and IL-1β were released starting at 3h after administration of Con A, and inhibition of the release of these cytokines attenuates the Con A-induced autoimmune hepatitis." (PMID 24498418, 2014).
autoimmune hepatitis (continued). "Taken together, these results indicated that ethyl pyruvate protected against Con A-induced autoimmune hepatitis by decreasing both early (TNF-α, IL-2, IL-1β and IL-6) and late (HMGB1) cytokine expression in mice." (PMID 24498418, 2014). "Recently, studies have reported that Con A-induced autoimmune hepatitis is largely mediated by the release of inflammatory cytokines such as IL-2, IL-4, IL-6, IL-10, IL-12, TNF-α and IFN-γ." (PMID 24498418, 2014). "Pretreatment with ethyl pyruvate ameliorated the pathological effects of Con A-induced autoimmune hepatitis and significantly decreased the levels of TNF-α, IL-2, IL-6 and IL-1β at 3h and 6h and the level of HMGB1 at 6h and 24h post injection." (PMID 24498418, 2014). "Indeed, a possible benefit of blocking TNF-α with infliximab to prevent liver tissue destruction has been shown in an adult cohort of patients with autoimmune hepatitis." (PMID 40607400, 2025). "One study demonstrated that LDN protects against the inflammatory response induced by autoimmune hepatitis, which may be related to its ability to suppress IL-6 and TNF-α secretion and interfere via modulation of the TLR4/NF-ƙB signalling pathways." (PMID 38720250, 2024). "On the other hand, activation of TNFR2 by agonistic antibodies or agonistic TNF muteins that activate, stabilize, and expand Tregs could have considerable therapeutic implications for treatment of autoimmune liver disease." (PMID 35122118, 2022). "In general, patients with autoimmune liver diseases display a different cytokine expression pathway compared with healthy patients, with increased serum levels of proinflammatory cytokines, such as IL-6, IL-8, and TNF-α." (PMID 30060508, 2018). "In addition, the fact that some TNF-α blockers are effective in different cholestatic autoimmune liver diseases in the presence of an inflammatory arthropathy is a particularly interesting, thought-provoking finding." (PMID 27876037, 2016). "Our results suggest that further studies examining the therapeutic role of this particular TNF-α blocker are warranted in cholestatic autoimmune hepatitis patients, and in particular in those individuals in whom the disease is associated with inflammatory arthropathies." (PMID 27876037, 2016). "We aimed to determine whether resveratrol could inhibit the expression and release of cytokines such as TNFα, IL-2, and IL-6 in ConA-induced autoimmune hepatitis." (PMID 26089871, 2015). "Case series and a pharmacovigilance database study have reported autoimmune hepatitis and other hepatobiliary events with anti-TNFα agents; a systematic review has also summarized biologic-related liver injury across agents, but head-to-head comparisons among TNF inhibitors remain scarce." (PMID 41601665, 2026). "Distinct molecular and biochemical mechanisms may underlie this association; for example, cytokines like interleukin-17 (IL-17) and tumor necrosis factor-alpha (TNF-α) are upregulated in autoimmune liver disease, driving chronic inflammation and raising graft rejection risk." (PMID 39597786, 2024). "In patients with autoimmune hepatitis (AIH), increased frequencies of TNF-producing CD4+ T cells were detectable in peripheral blood and liver biopsy specimens compared to healthy controls." (PMID 35122118, 2022). "On the contrary, paradoxically and in rare cases, anti-TNF therapy can trigger autoimmune-like diseases such as a lupus-like syndrome or autoimmune hepatitis (AIH) and might induce drug-induced liver injury (DILI)." (PMID 35122118, 2022). "On autoimmune hepatitis, CD4+ T cells represent the predominant population of T cells infiltrating into the liver, and Th1-like cytokines (e.g., IFN-γ and TNF-α) contribute to hepatic injury." (PMID 27679638, 2016). "Only a few clinical studies have reported the effects of anti-TNF therapy on mitigating the PBC in patients with RA and reducing TNF-producing CD4 + T cells, serum transaminases, and immunoglobulins in patients with autoimmune hepatitis." (PMID 37784156, 2023).
autoimmune hepatitis (continued). "The purpose of our study was to determine whether ethyl pyruvate could inhibit the expression and release of both early (TNF-α, IL-2, IL-6, IL-1β) and late (HMGB1 ) cytokines in Con A-induced autoimmune hepatitis." (PMID 24498418, 2014). "In a mouse model of autoimmune hepatitis, PTX demonstrated favorable hepatoprotection by improving serum aminotransferases and minimizing the hepatic inflammatory infiltrates through its marked anti-inflammatory actions that were proven by downregulation of TNF-α and interferon-γ." (PMID 38931349, 2024). "Escin could protect against Con A-induced autoimmune hepatitis in mice via suppressing infiltration of neutrophils, CD4+ T cells, and monocytes into the liver, activation of Nrf2/HO-1 signaling pathway, inhibiting TNF-α/NF-κB, TNF-α/JNK, and IL-22/STAT3 signaling pathways." (PMID 36063304, 2022).
rosacea (48 papers, 2011 to 2026). A chronic erythematous skin disorder that affects the face. "H. pylori infection can trigger a cytotoxic reaction inducing release of TNF-α and IL-8 due to the factor virulence cytotoxin-associated gene A (CagA), aggravating the inflammatory reaction involved in the pathophysiology of rosacea." (PMID 38260914, 2023). "It was found that rosacea is closely associated with a chronic inflammatory state, particularly with significantly elevated expression of genes such as IL6, OSM, and TNF‐α." (PMID 39823143, 2025). "These cells release molecules such as IL-1β, tumor necrosis factor, matrix metalloproteinases, reactive oxygen species, and the antimicrobial peptide cathelicidin, all contributing to inflammation in rosacea." (PMID 39859986, 2025). "Together, these findings suggest that rosacea and AD share convergent transcriptomic signatures, particularly NF-κB/IL-17/TNF-driven inflammation and vascular remodelling, while pointing to melatonin as a potential modulator." (PMID 41465136, 2025). "Probiotics, such as certain strains of Lactobacillus, Bifidobacteria and Saccharomyces, can positively influence several immune mechanisms that are implicated in rosacea pathogenesis by increasing IL10 and reducing TNF-a, IL-17A." (PMID 40149947, 2025). "TNF-α, IL-6, IL-1α, and IL-1β are well-characterized inflammatory mediators in rosacea pathogenesis, driving key pathological processes including inflammatory cell infiltration, vascular hyperreactivity, and neuroimmune disorder." (PMID 40378103, 2025). "Metformin is effective in improving rosacea-like lesions, reducing LL-37- and TNF-α-induced reactive oxygen production, and mitigating mitogen-activated protein kinase/NF-κB signal activation in keratinocytes." (PMID 39136023, 2024). "The underlying mechanism suggests that SIBO disrupts immunity, triggering rosacea by increasing the levels of TNF-α or other cytokines, reducing the level of IL-17, and stimulating Th1-mediated immune response." (PMID 39136023, 2024). "As for acquired immunity, patients with rosacea are reported to exhibit elevated TNF-α, IFN-γ, and IL-6, which can activate the JAK/STAT pathway." (PMID 39044833, 2024). "All other cytokines revealed comparable expression levels between acute flare-ups and chronic stabilized lesions, though TNF was significantly upregulated specifically in more chronic rosacea lesions." (PMID 36633910, 2023). "and pro-inflammatory cytokines (IL-8, IL-1β, TNF-α) in skin lesions implied that rosacea was not only a cutaneous inflammatory skin disorder but also with low-grade systemic inflammation." (PMID 36819686, 2023). "In rosacea, significantly higher expression levels of the Th1-signature cytokines, IFNγ, and tumor necrosis factor-α, also showed Th1 polarization." (PMID 36091020, 2022). "UV radiation, heat, spicy food, alcohol, stress, or microbes are known rosacea triggers that induce primary proinflammatory cytokines such as TNF-α and IL-1 family members." (PMID 35832851, 2022). "The activation of mast cells, macrophages, and toll-like receptor 2 and production of reactive oxygen species, MMP, tumor necrosis factor, and interleukin(IL)-1β are known to be involved in the inflammatory pathogenesis of both rosacea and IBD." (PMID 33182618, 2020). "Pro-inflammatory cytokines such as interleukin (IL)-1 β, IL-6, IL-8, and tumor necrosis factor-α are involved in rosacea pathogenesis, and inflammasome-related genes (CASP-1 and NALP-3) are overexpressed in skin samples from rosacea patients." (PMID 28968402, 2017). "For example, skin samples from patients with rosacea exhibit increased gene expression for proinflammatory cytokines such as IL-8, IL-1β, and TNF-α." (PMID 27649161, 2016). "Similarly, Yamasaki K’s study demonstrated an increased expression of TLR2 in rosacea patients, along with elevated levels of tumor necrosis factor-α (TNF-α), the main cytokine induced by TLR signaling." (PMID 40378103, 2025).